BCOR (BCL6 corepressor)
Diseases named in the same sentence as BCOR in open-access papers (continued):
Sharing a sentence is not in itself a finding about the gene and the disease.
melanoma (4 papers, 2015 to 2025). A malignant, usually aggressive tumor composed of atypical, neoplastic melanocytes. "Other alterations were found in genes reportedly altered in skin cancer, such as DGKI and SYK in melanoma or BCOR, PIKFYVE and NEDD4 in SCC." (PMID 28410231, 2017). "Immunohistochemically, the tumor cells were positive for S100 (5/6), cyclin D1 (2/3), SATB2 (2/3), BCOR (2/4), and TLE1 (1/3) while negative for MUC4 (0/6), keratin (0/5), EMA (0/4), desmin (0/6), CD34 (0/6), SMA (0/5), SOX10 (0/5), and pan melanoma (0/2)." (PMID 40705064, 2025). "Immunohistochemically, the tumor cells were positive for S100 (5/6), cyclin D1 (2/3), SATB2 (2/3), BCOR (2/4), and TLE1 (1/3) while negative for MUC4 (0/6), keratin (0/5), EMA (0/4), desmin (0/6), CD34 (0/6), SMA (0/5), SOX10 (0/5), and melanoma cocktail (0/2)." (PMID 40705064, 2025).
mesenchymal tumor (4 papers, 2024 to 2025). "Pathogenic alterations of BCOR have been reported in various tumor types including HGNET-BCOR-ITD, CNS tumor with BCOR/BCOR(L1)-fusion, endometrial stromal and soft tissue sarcomas, primitive myxoid mesenchymal tumors of infancy and undifferentiated round cell sarcoma." (PMID 38637838, 2024).
soft tissue sarcoma (4 papers, 2022 to 2025). A malignant neoplasm arising from muscle tissue, adipose tissue, blood vessels, fibrous tissue, or other supportive tissues excluding the bones. "These new “CIC fused” (CIC‐fused/ATXN1::NUTM1) and “BCOR rearranged” (BCOR fused/ITD/ YWHAE) soft tissue sarcomas (STS) are not well described." (PMID 37212486, 2023).
solitary fibrous tumor (4 papers, 2021 to 2025). Solitary fibrous tumor (SFT) represents a diverse group of ubiquitous rare spindle cell neoplasms that may be benign or malignant and that most frequently arises from the pleura and peritoneum and rarely from other sites such as head and neck, liver and skeletal muscle. "Diffuse strong nuclear expression of BCOR by immunohistochemistry is present, but molecular confirmation is needed, as patchy immunopositivity may be encountered in other tumors irrespective of BCOR mutational status, including solitary fibrous tumors." (PMID 35266242, 2022).
adenosarcoma (3 papers, 2020 to 2023). A low grade malignant neoplasm characterized by the presence of a benign epithelial component (tubular and cleft-like glands) and a low grade sarcomatous component that contains varying amounts of fibrous and smooth muscle tissues. "In our research, one patient was positive for BCOR; however, further analysis of BCOR rearrangements should be performed in adenosarcomas that demonstrate BCOR expression." (PMID 32972432, 2020). "Since BCOR was shown to be strongly expressed in adenosarcoma carrying the JAZF1-BCORL1 fusion gene, we examined the expression of BCOR in our case by immnohistochemistry using an anti-BCOR monoclonal antibody (clone C-10, Santa Cruz Biotechnology, Dallas, TX)." (PMID 36639698, 2023). "Genetic alterations in the Switch/Sucrose Non-Fermentable (SWI/SNF) chromatin remodeling complex components, such as SMARCA4 and BCOR, are recently reported in young high-grade uterine sarcomas, but their relationship with adenosarcomas remains unknown." (PMID 32972432, 2020). "Molecular testing, including for SMARCA4 and BCOR, might not be useful for predicting prognoses of adenosarcomas." (PMID 32972432, 2020).
chronic lymphocytic (3 papers, 2017 to 2025). "The BCOR N1459S mutation was not reported in HCL/HCLv but was documented most often in endometrial tumors and also in B-cell malignancies like chronic lymphocytic and prolymphocytic leukemia." (PMID 40669017, 2025).
Ewing family tumors (3 papers, 2021 to 2023). "Recently, in addition to Ewing family tumors, round cell sarcomas with EWSR1 gene fusion, BCOR-rearrangement, and CIC-rearrangement have been recognized as new entities; furthermore FISH and PCR are essential for the differential diagnosis between ES and Ewing family tumors." (PMID 36686838, 2022).
metastatic disease (3 papers, 2015 to 2023). "Our discovery of BCOR mutations being correlated with the development of metastatic disease may guide future systemic surveillance or management of these patients." (PMID 33466343, 2021). "Next-generation sequencing showed that the primary and lung metastatic tumors shared 4 mutations: PTEN (p.P248Lfs*8), CTNNB1 (p.D32A), BCOR (p.N1425S) and CBL (p.S439N)." (PMID 37328769, 2023).
spindle cell sarcoma (3 papers, 2020 to 2025). A malignant mesenchymal neoplasm composed of spindle-shaped cells. "Nevertheless, according to our results, GLI1, NKX2.2, and BCOR can also be expressed in SSs, representing a challenge in differential diagnosis with other small round/spindle cell sarcomas." (PMID 39062853, 2024).
Astrocytoma (2 papers, 2024). "We also present four adult diffuse glioma cases including GBM, IDH-Wildtype and Astrocytoma, IDH-Mutant with CREBBP fusions and describe the necessity of complementary molecular analysis in “CNS tumor with BCOR/BCOR(L1)-alterations for securing a final diagnosis." (PMID 38637838, 2024). "Variations of BCOR, MYCN, NOTCH1, and PIK3R1 and positive immunohistochemistry for S100 showed statistically significant results in univariate survival analysis in WHO grade 4 astrocytoma." (PMID 38970209, 2024).
B cell lymphomas (2 papers, 2023 to 2025). "BCOR disruptive mutations have been detected in several hematological malignancies, including B cell lymphomas and CLL." (PMID 40113912, 2025). "Furthermore, BCL6 interactions with co-repressor proteins BCOR and NCOR1/2, which were differentially expressed in our dataset, represent another key regulator of GC B cell function that is dysregulated in B cell lymphomas." (PMID 36619973, 2023).
Branchio-oculo-facial syndrome (2 papers, 2015 to 2024). "In humans, mutations in TFAP2A have been identified as a cause of branchio-oculo-facial syndrome (BOFS) and are linked to genes such as IGF6, BCOR, and P63, which are known to be connected with orofacial clefting." (PMID 39201474, 2024).
Congenital cataracts (2 papers, 2020 to 2023). "For example, in this study family 36 with congenital cataracts was found to harbor a heterozygous frameshift deletion (c.856del, p.[Ser286Alafs*92]) in BCOR (OMIM #300485), and this causes X‐linked dominant microphthalmia, syndromic 2 (OMIM #300166)." (PMID 32830442, 2020).
developmental delay (2 papers, 2023 to 2024). "The severe male X-linked recessive microphthalmia syndrome (“Lenz”) usually includes developmental delay and is caused by hypomorphic BCOR variants, mainly by a specific missense variant c.254C > T, p.Pro85Leu." (PMID 38957147, 2024). "Developmental disorders caused by mutations in GATAD2B (OMIM 615074), ADNP (OMIM 615873), BCOR (OMIM 300166) and NR2F1 (OMIM 615722) have features that overlap with those of TBR1-related disorder, including developmental delay, ID, speech and language impairments and autistic behaviors." (PMID 36579832, 2023).
kidney tumors (2 papers, 2015 to 2019). "We suggest the detection of the partial duplication inside exon 15 of BCOR as part of the diagnostic process of pediatric kidney tumors, representing a useful biomarker for the diagnosis of CCSK." (PMID 26516930, 2015). "Recently, CCSK has also been shown to consistently demonstrate BCOR gene abnormalities including exon 15 internal tandem duplications and BCOR-CCNB3 gene fusion which distinguish it from other pediatric renal tumors." (PMID 30736802, 2019). "ITD in the last exon of BCOR is recurrent in all CCSK samples analyzed, representing a valuable molecular marker to improve diagnosis of this rare childhood renal tumor." (PMID 26516930, 2015).
lung carcinoma (2 papers, 2020 to 2025). "BCOR is associated with improved immune checkpoint inhibitor responses when mutated in different types of lung cancer, and therefore could partly explain the exceptional benefit the patient saw with nivolumab/ipilimumab treatment." (PMID 40166913, 2025).
Microcornea (2 papers, 2020 to 2024). A congenital abnormality of the cornea in which the cornea and the anterior segment of the eye are smaller than normal. "Surprisingly, we detected a BCOR mutation in one patient with congenital aniridia and monocular microcornea." (PMID 39449022, 2024). "Our patient carrying BCOR c.4262G > A, who presented with congenital aniridia and monocular microcornea, had a phenotypic overlap with a patient carrying BCOR c.4870 C > T, as reported in a previous study." (PMID 39449022, 2024). "Loss-of-function mutations in the BCOR gene have been identified in individuals with oculo-facio-cardio-dental syndrome (OFCD), which includes microcornea, CC, and facial, cardiac, and dental abnormalities." (PMID 32883240, 2020).
myeloid leukemia (2 papers, 2015 to 2025). A clonal proliferation of myeloid cells and their precursors in the bone marrow, peripheral blood, and spleen. "Due to the limited number of patients in our study, and the rarity of BCOR mutations in pediatric myeloid leukemias, we cannot draw definitive conclusions." (PMID 40805145, 2025). "Mutations in the transcriptional co-repressor BCOR, which is targeted by somatic mutations in myeloid leukemia, was identified in one patient." (PMID 28721364, 2015).
neuroblastoma (2 papers, 2017 to 2025). Neuroblastoma (NB) is the most common solid, extracranial childhood tumor. "AHNAK mutations have been reported in other entities of neuroendocrine neoplasms (neuroblastomas and adrenocortical carcinomas, both with a frequency below 5%28), whereas BCOR mutations have been previously found in siNETs with a frequency of 5.6%29." (PMID 40410286, 2025).
thrombosis (2 papers, 2025). "Only TET2 missense mutations were significantly associated with prior arterial thrombosis, while BCOR mutations were significantly associated with prior venous thrombosis." (PMID 40533498, 2025). "Age greater than 60 years, the presence of the cardiovascular risk factors, mutation for thrombosis (DNMT3A, ASXL1, or BCOR/BCORL1), and previous thrombosis made part of this score." (PMID 41153823, 2025).
thymoma (2 papers, 2023 to 2024). A neoplasm arising from the epithelial cells of the thymus. "BCOR mutations consisted of a frameshift insertion in a B3 thymoma and missense substitutions in two B2 and one A TETs." (PMID 37671056, 2023). "Conversely, the other group of thymomas demonstrates a worse prognosis, and although a highly prevalent driver mutation has not been identified yet, BCOR mutations appear to be enriched within this subgroup." (PMID 37671056, 2023). "Individual genes specific to certain subtypes include BCOR in Type A thymoma, PBRM1 in Type AB thymoma, and BRD4 in Type B2 thymoma." (PMID 38338833, 2024).
uterine neoplasms (2 papers, 2020). "Seven cases diagnosed as LG-ESS were reclassified either as HG-ESS with BCOR rearrangement (n = 2), malignant epithelioid neoplasm with GLI1 rearrangement (n = 2), NCOA fusion-positive uterine tumors (n = 2) or uterine leiomyoma (n = 1)." (PMID 32933053, 2020).
Wilms tumor (2 papers, 2015 to 2018). An embryonal neoplasm characterized by the presence of epithelial, mesenchymal, and blastema components. "Gene expression analysis was evaluated with quantitative RT-PCR, compared to a control group of 5 Wilms tumors, showing that only CCSK were characterized by a consistent overexpression of BCOR (P = 0.004)." (PMID 26516930, 2015).
acute erythroid leukemia (1 paper, 2025). An acute myeloid leukemia characterized by a predominant immature erythroid population. "BCOR−/−DNMT3A−/− double-knockout mice develop an acute erythroid leukemia (AEL) phenotype." (PMID 40805145, 2025).
albinism (1 paper, 2020). A congenital disorder characterized by partial or complete absence of melanin pigment in the eyes, hair, or skin. "The genes identified for MAC were KMT2D, MAB2IL2, ALDH1A3; ASDA were KERA, PAX6, MYOC, TGFBI, and SLC4A11; congenital cataract were CRYBB2, EPHA2, HSF4 and BCOR; infantile nystagmus were CACNA1A and FRMD7; and albinism were OCA2, GPR143, HPS6 and SLC38A8." (PMID 32830442, 2020).
angiosarcoma (1 paper, 2022). A malignant tumor arising from the endothelial cells of the blood vessels.
cataract (1 paper, 2024). Partial or complete opacity of the crystalline lens of one or both eyes that decreases visual acuity and eventually results in blindness. "BCOR gene variants might be associated with PFV type of cataracts." (PMID 38874774, 2024).
central nervous system-primitive neuroectodermal tumors (1 paper, 2018). "In addition, a BCOR tandem duplication recently reported in central nervous system-primitive neuroectodermal tumors (PNETs) was found in one case (EP116) with grade III ST-EPN (data not shown)." (PMID 30514397, 2018).
cerebellar tumor (1 paper, 2020). "Additional CNS HGNET-BCOR cerebellar tumor, originally diagnosed as unclassified malignant neuroepithelial tumor, showed lack of exon 15 of BCOR gene duplication and negative reaction for GFAP and synaptophysin." (PMID 32650833, 2020).
coloboma (1 paper, 2007). An abnormality in which a part of a structure in one or both eyes is missing.
colon carcinoma (1 paper, 2017). "In a microarray screen conducted to identify endothelial genes regulated in response to tumor signals, BCoR transcripts were found to be 3.5-fold induced in ECs stimulated with conditioned medium from HT-29 colon carcinoma cells." (PMID 27880939, 2017).
colorectal cancer (1 paper, 2017). A primary or metastatic malignant neoplasm that affects the colon or rectum. "Since we found Bcl-6 and its co-repressor BCoR (Bcl-6 interacting co-repressor) to be regulated in human microvascular endothelium by colorectal cancer cells, we investigated their function in sprouting angiogenesis which is central to tumor growth." (PMID 27880939, 2017).
Cushing syndrome (1 paper, 2023). Cushing's syndrome (CS) encompasses a group of hormonal disorders caused by prolonged and high exposure levels to glucocorticoids that can be of either endogenous (adrenal cortex production) or exogenous (iatrogenic) origin. "In summary, we herein have reported gene fusions involving BEND2, BCOR and TFG in four successfully tested ACTH-producing and Cushing syndrome-associated NENs of the pancreas, but not in those from non-pancreatic origin." (PMID 36690805, 2023).
desmoplastic small round cell tumor (1 paper, 2025). Desmoplastic small round cell tumor (DSRCT) is an aggressive soft tissue cancer that typically arises in serous lined surfaces of the abdominal or pelvic peritoneum, and spreads to the omentum, lymph nodes and hematogenously disseminates especially to the liver. "However, despite its high sensitivity, CD99 is not entirely specific, as it is also expressed in a wide range of malignancies, including small round blue cell tumors like Ewing sarcoma, desmoplastic small round cell tumors (DSRCT), CIC-rearranged sarcomas, and BCOR-altered neoplasms." (PMID 40307756, 2025).
hepatocellular carcinoma (1 paper, 2021). A malignant tumor that arises from hepatocytes. "By targeting the BCL6 corepressor such as BCORL1, the migration and invasion of hepatocellular carcinoma (HCC) cells are restrained by miR-876-5p, which provides a new idea for the treatment of HCC." (PMID 33681362, 2021).
Hypodontia (1 paper, 2022). The absence of five or less teeth from the normal series by a failure to develop. "BCOR mutations are linked to dental anomalies, most of which are “deficiency defects,” such as oligodontia/hypodontia." (PMID 35957990, 2022).
infantile hemangiomas (1 paper, 2019). "BCOR may potentially be within a pathway of genes involved in PHACE syndrome and/or in infantile hemangioma formation." (PMID 31956451, 2019).
juvenile myelomonocytic leukemia (1 paper, 2025). A myelodysplastic/myeloproliferative neoplasm of childhood that is characterized by proliferation principally of the granulocytic and monocytic lineages. "He had PTPN11 and BCOR mutations and significant hepatosplenomegaly, suggestive of juvenile myelomonocytic leukemia (JMML) features." (PMID 40227821, 2025).
mature T-cell lymphoma (1 paper, 2021). "We have found the recurrent somatic mutation of BCOR occurred in mature T-cell lymphoma (TCL)." (PMID 33468080, 2021).
mesenchymal chondrosarcoma (1 paper, 2024). A morphologic variant of chondrosarcoma arising from bone and soft tissue. "Of the tumors reclassified as mesenchymal chondrosarcomas (cases 14 and 16), CD99 was strongly positive in case 14, while SATB2, BCOR, and MUC4 were negative." (PMID 38332052, 2024).
ovarian tumors (1 paper, 2020). "A break-apart FISH assay for BCOR, PHF1, and JAZF1 was negative in all components of the ovarian tumors." (PMID 32290854, 2020).
primary immunodeficiency (1 paper, 2025). "It is not classified as a primary immunodeficiency per se, but may arise in the context of acquired somatic mutations (e.g., STAT3, DDX3X, or BCOR) or immune dysregulation affecting EBV control." (PMID 40863427, 2025).
T cell lymphoma (1 paper, 2021). "Functional analyses indicated that K607E mutation of BCOR is oncogenic in nature and can serve as a genetic marker of T-cell lymphoma." (PMID 33468080, 2021). "In contrast to two nonsense mutations in BCOR, BCOR 1819 A > G (K607E substitution) was found at a high frequency in 15 of 47 NK/T cell lymphoma patients (31.9%)." (PMID 33468080, 2021). "In summary, we identified and functional characterized the K607E mutation of BCOR in T cell lymphoma." (PMID 33468080, 2021). "The K607E mutation of BCOR is oncogenic in nature and can serve as a genetic marker for T-cell lymphoma." (PMID 33468080, 2021). "Our data showed that the K607E mutation in BCOR—which results in the protein being unable to bind to BCL6— significantly enhanced cell proliferation, AKT phosphorylation, and IL-2 production in T cell lymphoma lines." (PMID 33468080, 2021).
uterine adenosarcoma (1 paper, 2023). "Both spindle cells in the corpus uteri and the intra-abdominal mass showed partial nuclear positivity for BCOR, suggesting that the intra-abdominal mass was a metastatic tumor derived from the preceding uterine adenosarcoma that may carry the JAZF1-BCORL1 fusion gene." (PMID 36639698, 2023). "Furthermore, both the uterine adenosarcoma and intra-abdominal mass were partially positive for CD10 and BCOR staining." (PMID 36639698, 2023).
Wilms renal tumors (1 paper, 2025). "Among the adherent cultures there were five cultures that later turned out to be derived from non-Wilms renal tumors according to reference pathology (2 CMN, 2 CCSK, 1 CN with the typical EGFR-ITD, BCOR-ITD and DICER1 mutations)." (PMID 39740515, 2025).